CD44 (CD44 molecule (IN blood group))
Diseases named in the same sentence as CD44 in open-access papers (continued):
Sharing a sentence is not in itself a finding about the gene and the disease.
cancer (continued). "When GSK3β is inhibited by AKT, free β-catenin accumulate and translocate to the nucleus, ultimately activating downstream target genes such as cyclin D1, C-Myc, CD44, FN1, C-JUN, Slug, L1CAM, and MMP14; thus contributing to tumorigenesis and EMT of cancer." (PMID 34546849, 2021). "CD44 regulates the phosphoinositide-3-kinase (PI3K)/AKT/mTOR signaling pathway and promotes the migration of cancer cells." (PMID 34361836, 2021). "The resistin treatment enhanced stemness in cancer cells by upregulating the stemness markers aldehyde dehydrogenase-1 (ALDH1), CD44, Oct4, Nanong and Sox2 and downregulating CD44 cell surface expression." (PMID 34588926, 2021). "Mechanistically, ZNF750 suppresses the expression of some cancer-related genes such as angiogenin, VEGF, RGS5, CD105, ITGA5, ITGB1, and CD44." (PMID 34288812, 2021). "The overexpression of BMI-1 and CD44 as CSC markers occurs in head and neck squamous carcinoma to promote cancer progression and mediate undesirable prognosis." (PMID 34769099, 2021). "Morphologic and biochemical assessments were performed on several groups of isolated lung CSCs displaying stem-like markers including CD133, CD44 and CD56, all of which have been identified to promote cancer recurrence and metastasis." (PMID 34527268, 2021). "RFX1 reduces cancer cell proliferation by targeting FGF1 and transforming growth factor beta 2 (TGFβ2), induce differentiation by targeting CD44 and c-Myc, and promote apoptosis by regulating myeloid cell leukemia sequence 1 protein (MCL1)." (PMID 33964962, 2021). "The gene expression of CRC cancer stem cell markers, including SOX2, OCT4, NANOG, KLF4, ALDH1A1, and CD44, were all highly expressed in CARMA3-overexpressed cells compared to control cells." (PMID 34885061, 2021). "A study found that the upregulation of TF FoxM1 mediated the acquisition of cancer stem-like cell characteristics in NSSLC H460 cells with analysis of stemness markers (CD133, ALDH1, and CD44)." (PMID 34745015, 2021). "Several studies conducted on HGSOC have demonstrated that cancer stem-like cells (CSC) are characterized by a set of markers such as ALDH1, CD44, CD117(c-KIT), and CD1332,3." (PMID 33828085, 2021). "The overexpression of cancer stems cell biomarkers such as CD133, OCT4, CD44, and ALDH1 is closely related to the recurrence and metastasis of cancers." (PMID 34803670, 2021). "To identify a cancer stem-cell-like subpopulation in MDA-MB-231 spheroid cells, we included stem cell markers, such as CD133, CD90, CD44, and CD24, and stem cell transcription factors such as SOX9 and Nanog." (PMID 34831064, 2021). "More particularly, the expression of CD44 and CD133 distinguishes a number of cancer-initiating cells." (PMID 34769230, 2021). "Our study showed that MBZ significantly induced DNA damage, cell cycle arrest, and downregulation of cancer stem cell markers CD44 and OCT3/4, and cancer progression-related ESM-1 protein expression in TNBC and RT-R-TNBC cells." (PMID 34500557, 2021). "CSC markers ALDH1A1, CD44, BMI1, OCT4, SOX2, and CD133 and their effects on cancer stemness, metastasis, prognosis, chemo/radiotherapy resistance and recurrence have been studied in HNSCC by our group and other researchers." (PMID 34359786, 2021). "Here, we observed a higher pro-angiogenic capacity of CD44+ TAMs in EPN and AEP, providing a plausible explanation for the different degrees of malignancy across cancer subtypes." (PMID 34824203, 2021). "NIR-PIT can also be used for programmed death-ligand 1 (PD-L1) expressing cancer cells, for CD25 for regulatory T cells (Tregs), and CD44 and CD133 for cancer stem cells." (PMID 34332294, 2021). "To further evaluate the biological and inhibitory effects of NSC765600 and NSC765691 in cancer, we identified CCND1/CDK4/PLK1/CD44 as potential druggable candidates for both compounds by using online prediction tools." (PMID 34063946, 2021).
cancer (continued). "We identified the cancer cells with stem-like characteristics in DU145 and PC3 cells as the CD44+/CD24- subpopulation." (PMID 33661931, 2021). "There are some biomarkers for immature subpopulations in several cancers, such as aldehyde dehydrogenase (ALDH) and CD44 13, 14, 15, 16 and are often used to evaluate cancer cell stemness." (PMID 33611864, 2021). "Additionally, DDM cellular uptake was significantly decreased in normal cells, suggesting the CD44 and FR-α dependent uptake, which facilitated the enhanced intracellular drug concentration toward both CD44 and FR-α receptors which overexpressing in cancer cells." (PMID 34771733, 2021). "To determine the effect of LR004-VC-MMAE on CSCs, we first investigated the fraction of CSCs by assessing the expression of CSC markers CD44, CD24 and CD133 in cancer cells by flow cytometry." (PMID 34879870, 2021). "CD44 promotes the proliferation, adhesion, and invasion of cancer cells, while overexpression of ECAD decreases the invasion of cancer cells." (PMID 35008821, 2021). "Exposure of NSCLC cells to γ-radiation increased the cellular levels of ALDH1 activity and CD44 expression, which are representative biomarkers that impart chemo- or radio-resistant CSC properties to cancer cells." (PMID 34163000, 2021). "E-selectin recognizes sialylated carbohydrates/fucosylated glycoprotein ligands such as ESL-1, PSGL-1, CD44 and CLA, among others, that are expressed on circulating leukocytes and overexpressed on cancer cells." (PMID 33477563, 2021). "CD44 is therefore a major actor of HCV pathogenesis, and together with its ligand osteopontin, emerges as a key regulator of cancer stem cells and HCV replication." (PMID 34065048, 2021). "As reported, CD44 expression level is positively correlated with PD-L1, PD-1, IL10, and TGFB1 expression in some cancers." (PMID 35187044, 2021). "Cancer stemness markers (ALDH1, CD44, OCT-4, and SOX-2) highly increased when comparing to the cell subpopulation with low ALDH1 expression (ALlow)." (PMID 34163000, 2021). "As reported, the cancer cells that undergo EMT process can acquire cancer stem-like properties and showed an increase in CD44 expression." (PMID 34681583, 2021). "Results demonstrate that the extract, at IC50 doses, was able to significantly decrease the expression of CD44, CD24, NANOG, SOX-2, and OCT-4, indicating a reduction in the amount of cancer stem cells (CSCs) in the culture." (PMID 33572111, 2021). "Nrf2 knockdown reduced the expression of cancer stemness markers EPCAM, CD44 and Nanog in sorafenib-resistant Huh7 cells." (PMID 34473785, 2021). "The role of CD44 and KIF20A in tumors has been well studied, and they are upregulated in a variety of cancers." (PMID 33816274, 2021). "CD44+ cells were isolated from NPC cell lines and exhibited the characteristics of cancer stem cell or cancer progenitor cells such as pluripotent markers, self-renewal ability and chemo- and radiation-resistance." (PMID 34407150, 2021). "The roles of TIPRL/LC3/CD133/CD44/CD46 in liver normal and cancer cell lines were determined by in vitro studies." (PMID 34208132, 2021). "Five of these 25 alternatively spliced genes are well-known to play a role in cancer (ARHGEF11, CD44, CTNND1, ENAH, MBNL1)." (PMID 33845831, 2021). "The populations of CD44- and CD133-, which are considered markers of cancer stem cells, positive cells were analyzed by flow cytometry." (PMID 33462372, 2021). "Next, we will focus mainly on integrin, DDRs, CD44, and RHAMM, which are frequently discussed in the context of cancer." (PMID 33888679, 2021). "CD10+GRP77+ CAFs promote sphere formation, the proportion of ALDH+ and CD44+CD24– breast CSCs, and chemoresistance properties of cancer cells by secreting IL6 and IL8." (PMID 34760886, 2021). "Autocrine IGF-1 signaling is responsible for regulating cancer stem cell (CSC) related markers (e.g., CD44+, ALDH+, and EpCAM+) in MHCC97H cells." (PMID 33669204, 2021).
cancer (continued). "Serglycin (SRGN), a proteoglycan secreted from cancer cells and CAFs, renders chemoresistance and EMT features via a CD44-dependent NF-κB activation." (PMID 34760886, 2021). "And the results showed a higher expression of JUP and ITGB4 in cells expressing CD44 or CD24, which were cell markers of cancer stem cells." (PMID 34402716, 2021). "Immunocytochemistry showed a significant ratio of the KAIMRC2 cells’ expressing key breast epithelial and cancer stem cells (CSCs) markers, including CD47, CD133, CD49f, CD44, and ALDH-1A1." (PMID 34073849, 2021). "The multicellular-TME cultures further induced the survival of cancer stem cells (CSCs) (upregulation of CD133, CD44, and ALDH1)." (PMID 34660256, 2021). "In this study, we found that MKL-1 not only promoted the stem cell characteristics of cancer cell MGC-803, but also played a regulatory mechanism through the miR-17/CD44/EpCAM pathway." (PMID 34239355, 2021). "After 14-days of PSCs culture under the Ndn and Bdn influence, immunofluorescence analysis of CD44 and CD133—surface markers identifying a subset of cancer stem cells—was performed." (PMID 34769230, 2021). "Since markers such as CD44 and CD133 have been used to facilitate normal and cancer stem cell identification, we next examined their protein expression in adherent cell lines following CCNP upregulation using lentiviral vectors." (PMID 34604945, 2021). "Upon exposure to natural agents, a significant decrease occurs in levels of CSC markers including CD44, CD133, ALDH1, Oct4 and Nanog to impair cancer stemness." (PMID 34769099, 2021). "To verify that the spheres in our setup were enriched in cancer stem cells, we tested the expression of the stemness-related transcription factors POU5F1 (Oct4), SOX2, CD44, PROM1 (CD133), and NANOG in spheres and adherent cells 72 h after seeding." (PMID 34832951, 2021). "Similar to other cancer cells, CSCs of head and neck SCC express surface markers such as CD44 and CD133, which are used for identification." (PMID 33681421, 2021). "These specific cancer cells are called cancer stem cells (CSCs), which are detected mainly with the expression of specific cell surface markers (CD24+, CD44+, or CD133+; alone or combined expression)." (PMID 34206730, 2021). "Our approach was consistently repeated for the conjugation of antibodies against CD44 and EGFR, which are prominent cancer cell markers." (PMID 34959436, 2021). "CD24, CD44, and CD133 expression decreased after SPNs treatment both in PANC-1 spheroid cells and PANC-1 cancer cell line." (PMID 34094034, 2021). "Cisplatin, targeting CD44+/CD117+ cells overexpressing CXCR4, was used to inhibit metastasis and limit invasion of cancer-initiating cells." (PMID 34439332, 2021). "The CD44-induced epithelial-mesenchymal transition (EMT), however, is strongly correlated with cancer metastasis and is regulated by TGF-β1." (PMID 34361836, 2021). "designed and developed a poly (lactic-co-glycolic acid) (PLGA) nanoparticle for the CD44-targeted delivery of anticancer drug molecules, salinomycin (SLM) to kill cancer stem cells (CSCs) and paclitaxel to weaken cancerous cells." (PMID 35431911, 2021). "The PI3K/Akt, Wnt, STAT3, NF-κB and Sonic signaling pathways undergo down-regulation by natural products to reduce expression level of CSC markers including CD44, CD133, Notch, Oct4 and Nanog, impairing cancer stemness and progression." (PMID 34769099, 2021). "While some cell surface markers, such as CD44, CD24, and CD133, have been identified as common CSC markers for almost all cancer types, CSC in GC and EC cancers present their specific markers as well." (PMID 34012400, 2021). "CD44 plays a pivotal role in regulating CSC stemness properties, and, along with the CD44v isoform, has been suggested as a biomarker and a therapeutic cancer target." (PMID 34946546, 2021).
cancer (continued). "Recent evidence showed that miR-34a targets both CD44 and CD133 and this resulted in the suppression of cancer stem cell features, such as self-renewal capacity, in various cancer cells." (PMID 33673143, 2021). "Here, we suggest TSPYL5 as a novel cancer stemness factor that simultaneously activates ALDH1 and CD44 transcription." (PMID 34163000, 2021). "CD44 regulates the phosphoinositide-3-kinase (PI3K)/AKT/mTOR signaling pathway and promotes cancer cell migration." (PMID 33925400, 2021). "Cancer cells from all fifteen samples were filtered and categorized into nine clusters, among which C6 is characterized with BCSC biomarkers including CD44 and ALDH." (PMID 34611125, 2021). "The proteolytic cleavage of CD44 was high in U251MG, A549, and H1299 cell lines, compared to other cancer cell lines tested; these cell lines were therefore selected for further studies." (PMID 33804427, 2021). "Nuclear PKM2 binding to Oct4 can upregulate cancer stemness-related genes (CD133, CD44, LDHA, NANOG), thus promoting the CSCs population’s enrichment from several human cancer types." (PMID 33828530, 2021). "Several aptamers, available against CSC markers (CD44, CD133, ABCG2, etc.), can be used as a bait to trap cancer stem cells from a heterogeneous population." (PMID 34575825, 2021). "When compared with those in low-grade PCa tissues with Gleason scores of 6 (control), the ALDH, CD44, CXCR4 and CD24 protein levels were generally elevated in para-carcinoma tissues." (PMID 34247196, 2021). "In contrast, AS906 and AS914, which derived from carcinomas with sarcomatoid features and formed loose spheroids in culture, expressed ZEB1, SNAI2, CD44, and Vimentin, but negligible levels of EpCAM and E-Cadherin (CDH1)." (PMID 33941777, 2021). "In the present study, we also found that GATA5 synergized with Paclitaxel to inhibitexpression of the stemness markers CD44 and CD133 in the cancer stem cells." (PMID 32779438, 2020). "We observed that cancer stem cell markers, CD133 and CD44, are expressed in all cell types studied, though at different levels." (PMID 32188032, 2020). "More studies will be focused on investigating how UBE2C regulating these cancer markers including ALDH1A2, CD44, CD166 and EpCAM and the relationship between these cancer markers for cancer stemness in vitro." (PMID 32899896, 2020). "We then analyzed the effect of Lin28A on the proportion of OC cancer stem cell marker CD133+, CD44+, and ABCG2+ cells by flow cytometry." (PMID 32398961, 2020). "MCF-7/SC displayed an enriched CD44+/CD24− cell population compared to MCF-7 cells, indicating the characteristics of cancer stem cells." (PMID 32503225, 2020). "Different cell markers have been proposed for the definition of cancer stem cells in OSCC, including CD44, CD133, ALDH, cMET and GRP78." (PMID 32899449, 2020). "In conclusion, this study suggests pKAL exhibits anti-cancer effects on RT-R-MDA-MB-231 cells, by suppressing CD44 and Oct 3/4, β-catenin and MMP-9 which appeared to be linked to the RT resistance of RT-R-MDA-MB-231 cells." (PMID 32326231, 2020). "HB cells can express CD44, CD90, CD133, and other cancer stem cell markers, suggesting that cancer stem cells also exist in HB." (PMID 32758256, 2020). "Several other genes residing at the association loci reported include known drug targets with repurposing opportunities, such as GRK6, CD44, SLC38A10, and ADK, with potential implications across multiple different cancers and auto-inflammatory diseases." (PMID 31937769, 2020). "MUC1 and MUC4 induced by IL-17RB upregulate expression of cancer stemness-related genes, such as SOX2, Nanog, Oct-4, and surface CD44 to facilitate sphere formation." (PMID 33082357, 2020). "CD24‐/CD44+ cancer cells show more significant stemness and resistance than CD24+/CD44+ cancer cells, and there is inherent resistance to radiotherapy." (PMID 32991066, 2020).
cancer (continued). "Flow cytometry revealed expressions of normal stem cell markers (SSEA3, SSEA4, and LGR5) and cancer stem cell markers (CD24, CD44, CD117, ROR1, and CD133)." (PMID 32035490, 2020). "During the last decade, several studies have shown that CD44 and STAT3 cooperate in cancer promotion." (PMID 33335857, 2020). "Polysaccharide hyaluronic acid (HA) acts as a cancer-targeting ligand when connected with MOF, too, because it recognizes the overexpressed CD44 that occurs in many cancer cells." (PMID 32850658, 2020). "Biomarkers of breast CSCs, including CD44 and aldehyde dehydrogenase 1 (ALDH1), can be regulated during cancer progression and metastasis." (PMID 33352739, 2020). "Several genes in the cell adhesion molecule category, such as CD44 and CADM1, were involved in cancer cell migration and the regulation of ECM adhesion." (PMID 32315343, 2020). "Our results indicated that knockdown of UBE2C decreased the expression levels of these cancer stemness markers including ALDH1A2, CD44, CD166 and EpCAM in both Ca9-22 and SAS cells." (PMID 32899896, 2020). "We compared the expression of putative cancer stem cell markers (CD24, CD44, CD117, ROR1, and CD133) of HGSC [31134503] at P2 and P8, as well as two HGSOC cell lines." (PMID 32035490, 2020). "As a result, we ascertained that CD44, PLOD1 and PLOD2 played a pro-cancer role in RCC through vitro experiments, reiterating that glycolytic risk signature was closely associated with RCC progression." (PMID 33287763, 2020). "Along with the fact that CD44( + )/CD45(−) CTCs show some degree of chemotherapy resistance, they have also been shown to exhibit other characteristics of cancer stem cells (CSC)." (PMID 32183503, 2020). "The analysis of 942 cases of cancer tissues revealed a significant positive correlation among RUNX2, BRG1, and CD44." (PMID 33071648, 2020). "We successfully derived FTEC with the expression of the normal stem cell markers (LGR5, SSEA3, and SSEA4), cancer stem cell markers (CD24, CD44, CD117, ROR1, CD133, and ALDH), and characteristics of stem cell." (PMID 32035490, 2020). "Cancer stem cells (CSCs) expressing stem cell markers (e.g., CD133, CD44) and transcription factors (e.g., OCT3/4, SOX2, KLF4, c-MYC) have been identified to exhibit undifferentiated (stem cell-like) and tumorigenic properties." (PMID 32389123, 2020). "Meanwhile, we also analyzed the protein and mRNA expressions of RUNX2, BRG1, and CD44 in the CRC tissues and found that their protein and mRNA levels were more elevated in the CRC tissues than in the adjacent cancer tissues." (PMID 33071648, 2020). "The deregulated proteins found in the pools of cancer vs. control serum samples—PEDF, IGKC, CD44, and CST3—have been previously reported." (PMID 33224883, 2020). "Another important goal is the targeting of cancer-specific antigens using a cancer-specific mAb (CasMab) because EGFR, HER2, PODXL, and CD44 are widely expressed in normal tissues." (PMID 33000243, 2020). "Key cancer-related pathways and proteins that these genes can regulate include the AKT/GSK-3β/SNAIL pathway, MMP-9, CD44 and STMN1 which are involved in EMT and metastasis." (PMID 33374923, 2020). "Below, we summarize currently existing evidence of functional and direct collaborations between CD44 and STAT3 signaling pathways across various cancer models." (PMID 33335857, 2020). "In cancer, MIF predominantly signals through binding with the CD74 receptor, however, binding through the chemokine receptors CXCR2, CXCR4, and CD44 have also been shown." (PMID 32317702, 2020). "As spheroid formation is a key attribute of cancer stem cells (CSCs), and points towards the presence of cancer stem cell-like properties, we analyzed accepted CSC markers (CD44 / CD24)." (PMID 32276641, 2020).